SPG7 (SPG7 matrix AAA peptidase subunit, paraplegin)
Diseases named in the same sentence as SPG7 in open-access papers (continued):
Sharing a sentence is not in itself a finding about the gene and the disease.
Cognitive impairment (6 papers, 2014 to 2022). Abnormal cognition is characterized by deficits in thinking, reasoning, or remembering. "Two of our patients with cerebral and CC atrophy underwent cognitive testing and showed signs of cognitive impairment suggesting a potential role of rare heterozygous SPG7 variants in the ALS-FTD disease spectrum." (PMID 32447552, 2020). "Similarly, cognitive impairment in SPG7-associated HSP has been demonstrated in a family with three HSP patients harboring the same homozygous SPG7 variant and in another case with HSP type 7." (PMID 32447552, 2020). "The FTD-specific cognitive impairments disturbed executive function and reduced verbal fluency were identified by ECAS in the SPG7 variant carrier MD087." (PMID 32447552, 2020). "Patients with SPG7 may have cognitive impairments and psychosis, displaying specific characteristics, which should be of concern." (PMID 35637455, 2022). "Severe cognitive impairment was also described in other less frequent genetic types of complicated HSP including SPG15 and the AP4-related HSP genes, but seems to be absent or mild in most patients with pure HSP, including SPG4, SPG5, and SPG7." (PMID 35906604, 2022).
optic neuropathies (6 papers, 2011 to 2025). "As this genetic disease is recessive, this variant can only confer susceptibility to optic neuropathy, but it could act synergistically with the SPG7 variant to increase susceptibility to optic nerve damage." (PMID 38796496, 2024). "Although probably very uncommon, the possible involvement of AFG3L2 and SPG7 in optic neuropathies should prompt the screening of these genes in isolated and syndromic DOA patients, negative for OPA1 and OPA3 mutation." (PMID 26539208, 2015). "Mutations in SPG7 have been identified in an autosomal recessive form of HSP, and in some patients, bilateral optic neuropathy is a prominent clinical feature further complicating the neurological phenotype (HSP-7, OMIM 607259)." (PMID 21112411, 2011). "Several of these genes, such as WFS1, SPG7, and NR2F1, are common causes of hereditary optic neuropathies and none of them has been previously associated with alcohol susceptibility, to the best of our knowledge." (PMID 38796496, 2024). "Optic neuropathy is frequently observed in ARCAs, particularly in those forms primarily related to damage of mitochondrial pathway such as FRDA, SPG7, ARSACS, where retinal GCs death is a specific target for mitochondrial mediated neurodegeneration in the retina." (PMID 38390227, 2023).
spastic paraplegia type 7 (6 papers, 2016 to 2025). "The pathogenic variants of the SPG7 gene are associated with hereditary spastic paraplegia type 7 (HSP7)." (PMID 39978794, 2025). "SPG7 is linked to hereditary spastic paraplegia type 7 (SPG7, MIM #607259)." (PMID 40857737, 2025). "Large deletions can also be found in the SPG7 gene that is responsible for spastic paraplegia type 7, another form of autosomal recessive spastic paraplegia." (PMID 29875629, 2018).
amyotrophic lateral sclerosis (5 papers, 2017 to 2026). Amyotrophic lateral sclerosis (ALS) is a neurodegenerative disease characterized by progressive muscular paralysis reflecting degeneration of motor neurons in the primary motor cortex, corticospinal tracts, brainstem and spinal cord. "Several reports have suggested that heterozygous SPG7 variants may also play a role in HSP, but also in amyotrophic lateral sclerosis (ALS)." (PMID 41877227, 2026).
breast carcinoma (5 papers, 1997 to 2024). "In sporadic breast cancer samples with LOH at 16q24.3, single nucleotide polymorphisms in exon 11, intron 7, intron 10, and intron 12 were detected in the SPG7 gene." (PMID 38138918, 2023). "For example, SPG7 interacts with a high proportion of the clients that it can in thyroid cancer (THCA) but with a low proportion in breast cancer (BRCA)." (PMID 37805501, 2023). "Promising proteomic markers of breast cancer (SPG7, ADRB1, SMCO4, PHF1, and PSMG1) from NPCs identified in this study should be further verified in larger patient groups." (PMID 38138918, 2023). "These genes included BPTF, PHF5A, and SPG7 in cancer of female genital organs, as well as FGF10, NFIX, and SCAP in breast cancer." (PMID 38409266, 2024). "For instance, in breast cancer, the CLPP chaperone realizes about 40% of its potential, while SPG7 realizes about 15%." (PMID 37805501, 2023).
Dystonia (5 papers, 2011 to 2023). An abnormally increased muscular tone that causes fixed abnormal postures. "Patients with SPG7 may have complex or mixed phenotype including the presence of parkinsonism, dystonia, and tremor." (PMID 38035585, 2023). "Dystonia was previously observed in a family whose affected members carried an 18p chromosomal deletion that included AFG3L2, and Afg3l2+/-Spg7-/- mice also exhibited dystonic features." (PMID 22022284, 2011).
progressive external ophthalmoplegia (5 papers, 2015 to 2025). A mitochondrial myopathy characterized by slowly progressive paralysis of the levator palpebrae, orbicularis oculi, and extraocular muscles. "SPG7 variants are associated with a spectrum of mitochondrial disorder phenotypes, including progressive external ophthalmoplegia, and myopathy." (PMID 39978794, 2025). "The SPG7 p.Ala510Val variant has been previously reported in patients with AR HSP, whereas the p.Arg486Gln has been previously reported in both AR HSP and progressive external ophthalmoplegia (PEO)." (PMID 32397312, 2020).
ptosis (5 papers, 2011 to 2025). The drooping of the upper eyelid. "Due to involvement of skeletal muscle in mitochondrial disease, PEO and ptosis can also be seen due to variants in SPG7." (PMID 41149856, 2025). "Given our ascertainment methods, it is not surprising that the majority of the patients with SPG7 mutations had PEO, usually associated with marked ptosis." (PMID 24727571, 2014).
Atrophy (4 papers, 2015 to 2025). Any weakening or degeneration, especially through lack of use. "Recessive mutations in SPG7, encoding paraplegin, lead to hereditary spastic paraplegia (HSP), a neurodegenerative disease affecting the long corticospinal motor axons, while dominant mutations in AFG3L2 cause spinocerebellar ataxia type 28 (SCA28), associated with atrophy of the cerebellum." (PMID 27911893, 2016).
chronic progressive external ophthalmoplegia (4 papers, 2014 to 2020). "SPG7 encodes an ATP-dependent proteolytic complex of the mitochondrial inner membrane reported as pathogenic for chronic progressive external ophthalmoplegia through disordered mitochondrial DNA maintenance." (PMID 31345272, 2019).
neuropathy (4 papers, 2016 to 2025). A disorder affecting the nervous system that manifests with pain, tingling, numbness, and/or muscle weakness. "We found that 1.097% (120 of 10,935) of GPAP participants harbour pathogenic or likely pathogenic heterozygous SPG7 variants, while only 0.240% (5 out of 2,087) of our neuropathy cohort." (PMID 38549004, 2024). "In an attempt to elucidate this association further, we assessed the frequency of heterozygous SPG7 variants within our neuropathy cohort." (PMID 38549004, 2024). "The putative role of these heterozygous SPG7 variants in the aetiology of neuropathies remains controversial." (PMID 38549004, 2024). "Indeed, we identified four families with neuropathy as the predominant or sole clinical feature, harboring variants in genes causing complex neurological syndromes, such as SPG7, FXN, and ATM." (PMID 39776111, 2025). "To gain a better insight whether this association is real, we tested the frequency of heterozygous SPG7 variants in our neuropathy cohort, compared to the wider GPAP." (PMID 38549004, 2024). "The role of SPG7 heterozygous variants in the aetiology of neuropathies is currently disputed." (PMID 38549004, 2024). "This decreased prevalence in our neuropathy cohort does not support the pathogenic role of heterozygous SPG7 mutations in the aetiology of mitochondrial neuropathies." (PMID 38549004, 2024).
Nystagmus (4 papers, 2020 to 2025). Rhythmic, involuntary oscillations of one or both eyes related to abnormality in fixation, conjugate gaze, or vestibular mechanisms. "The individual carrying the heterozygous SPG7 variant in this study (Case 2) was born full term and developed strabismus and nystagmus, but was not diagnosed with bilateral ONH until he was 17 years of age despite blindness." (PMID 32040484, 2020).
paraplegia (4 papers, 2017 to 2025). Complete paralysis of the lower half of the body including both legs, often caused by damage to the spinal cord. "Mutations in SPG7 and RYR1 genes are associated with muscle developmental impairment causing paraplegia and myopathy, respectively." (PMID 34125832, 2021).
frontotemporal dementia (3 papers, 2009 to 2021). Frontotemporal dementia (FTD) comprises a group of neurodegenerative disorders, characterized by progressive changes in behavior, executive dysfunction and language impairment, as a result of degeneration of the medial prefrontal and frontoinsular cortices. "Moreover, some of the genes identified in ALS patients are also causative for other neurodegenerative disorders, such as C9orf72 and TARDBP for frontotemporal dementia (FTD) and Parkinson’s disease, and SPG7 and SPG11 for hereditary spastic paraplegia, indicating shared pathomechanisms." (PMID 35052424, 2021).
autosomal recessive spastic paraplegia (2 papers, 2023 to 2024). "The remaining significant gene, SPG7, has previously been associated with autosomal recessive spastic paraplegia." (PMID 39669630, 2024). "Whole genome sequencing on the other hand revealed two distinct variants in the SPG7 coding region, a well-studied gene that causes an autosomal recessive spastic paraplegia as well as recessive cerebellar ataxias." (PMID 38239855, 2023).
axonal motor neuropathy (2 papers, 2016 to 2020). "NCS showed a predominantly axonal motor neuropathy in all SPG7 variant carriers attributable to loss of motor axons in ALS, and additionally an axonal sensory neuropathy in three SPG7 variant carriers (VALS125, MD075, MD018)." (PMID 32447552, 2020). "Distal axonal motor neuropathy and neurogenic changes were detected in 23 subjects: most of the SPG7, SPG11, SPG15 and SPG35 patients, the eldest three SPG3a patients, a minority of SPG4 (5 out of 23) and one SPG5 subject." (PMID 27077743, 2016).
Brain atrophy (2 papers, 2013 to 2020). Partial or complete wasting (loss) of brain tissue that was once present. "MRI analysis showed varying degrees and patterns of brain atrophy consistent with a pattern suggestive of FTD in three cases carrying SPG7 variants (VALS008, VALS125, VALS093)." (PMID 32447552, 2020). "This is in sharp contrast to mouse models of pure HSP like SPG4, SPG7 or SPG31, where no cortical motoneuron loss had been reported and corresponds with reports from SPG15 patients, which also display variable degrees of brain atrophy." (PMID 24367272, 2013).
colorectal cancer (2 papers, 2016 to 2022). A primary or metastatic malignant neoplasm that affects the colon or rectum. "SPG7 matrix AAA peptidase subunit paraplegin (SPG7) codes for a mitochondrial metalloprotease protein and is upregulated in colorectal cancer." (PMID 36139405, 2022).
Coronary Artery Disease (2 papers, 2016 to 2025). "However, some studies demonstrated that UPRmt elements are associated with heart damage, including eIF2α and cardiomyocyte apoptosis and heart failure, OMI and cardiomyocyte apoptosis, SPG7 and coronary artery disease, and HSP60 and heart failure." (PMID 40426970, 2025).
motor neuron disease (2 papers, 2025 to 2026). "In our cohort, 3.4% of patients with suspected motor neuron disease (without amyotrophy) had biallelic SPG7 RDVs, and 4.3% had monoallelic RDVs." (PMID 39978794, 2025).
recessive spastic paraplegia (2 papers, 2018 to 2023). "We detected a maternally inherited heterozygous variant in SPG7 in one of the subjects that has been reported to be pathogenic in patients with recessive spastic paraplegia." (PMID 29490693, 2018).
spinocerebellar ataxia type 28 (2 papers, 2021). Spinocerebellar ataxia type 28 (SCA28) is a very rare subtype of type I autosomal dominant cerebellar ataxia (ADCA type I). "Mutations in AFG3L2 and SPG7 have been initially identified as the cause of spinocerebellar ataxia type 28 (SCA28) and spastic ataxia type 5, and hereditary spastic paraplegia type- 7 (HSP7), respectively." (PMID 33806088, 2021).
Alexander disease (1 paper, 2023). Alexander disease (AxD) is a rare neurodegenerative disorder of the astrocytes comprised of two clinical forms: AxD Type I and Type II manifesting with various degrees of macrocephaly, spasticity, ataxia and seizures and leading to psychomotor regression and death. "Subsequently, HSP-SPAST (SPG4), HSP/ATX-SPG7 (SPG7) as well as ATX-ATXN1 (SCA1), ATX-ATXN2 (SCA2), ATX-ATXN3 (SCA3), ATX-CACNA1A (SCA6), ATX/HSP-SACS (ARSACS), and Alexander’s disease (GFAP) were excluded." (PMID 36768210, 2023).
atherosclerosis (1 paper, 2021). A disease characterized by the build-up of fatty material and calcium deposition in the arterial wall resulting in partial or complete occlusion of the arterial lumen. "Of these genes, A2ML1, AGGF1, CBS, ECE1, GABRB3, GALNT2, MRPS6/SLC5A3, and SPG7 had documented associations with hypertension, ischemic stroke and methionine metabolism, atherosclerosis, and early-onset MI." (PMID 34252155, 2021).
bipolar disorder (1 paper, 2023). A disorder of the brain that causes unusual shifts in mood, energy, activity levels and the ability to carry out day-to-day tasks. "4/30 placental genes (TSTA3, BRD8, WDR82, SPG7) that were associated with both schizophrenia and bipolar disorder had opposite signs, so they were predicted to be up-regulated in the placentae of individuals who developed one disorder and down-regulated in the other disorder." (PMID 37188697, 2023).
cerebellar degeneration (1 paper, 2011). Degeneration of the cerebellum. "Of particular interest, double mutant Spg7-/-Afg3l2+/- mice exhibit a unique phenotype with severe early-onset spasticity and impairment of cerebellar function that is associated with axonal and cerebellar degeneration." (PMID 22022284, 2011). "Our patients' features closely resemble those of the Afg3l2+/-Spg7-/- mice -- early-onset axonopathy and cerebellar degeneration, as well as mitochondrial DNA depletion." (PMID 22022284, 2011).
COVID-19 (1 paper, 2022). A disease caused by infection with severe acute respiratory syndrome coronavirus 2. "Interesting, a new report revealed that SPG7 is upregulated upon SARS-CoV-2 infection, suggesting a role of PTP-mediated mitochondrial dysfunction in determining COVID-19 development and associated myocardial injury." (PMID 35005527, 2022). "Having observed a robust elevation of CCDC58 and Ca2+ dependent functional changes of mitochondrial energetics in COVID-19 patients, we sought to identify SARS-CoV-2 proteins that bind to SPG7 in the mitochondria." (PMID 35005527, 2022).
dominant optic atrophy (1 paper, 2025). "The gene SPG7 has also been shown to cause isolated dominant optic atrophy (DOA)." (PMID 41149856, 2025).
hereditary optic neuropathy (1 paper, 2022). "SPG7 should be considered in the workup of suspected hereditary optic neuropathy." (PMID 35243150, 2022).
multifocal dystonia (1 paper, 2022). A dystonia that involves two or more unrelated body parts. "MD-159 (SPG7 p.A510V/p.A572V), previously reported, presented early onset multifocal dystonia with severe cranio-cervical involvement and mild CA on brain MRI." (PMID 36233161, 2022).
myoclonic epilepsy (1 paper, 2011). A group of epilepsy syndromes in which myoclonic seizures are a prominent feature. "This produced an early-onset clinical syndrome that combines the severe phenotypes of SPG7 and SCA28, in additional to other “mitochondrial” features such as oculomotor apraxia, extrapyramidal dysfunction, and myoclonic epilepsy." (PMID 22022284, 2011).
progressive supranuclear palsy (1 paper, 2015). A rare late-onset neurodegenerative disease characterized by supranuclear gaze palsy, postural instability, progressive rigidity, and mild dementia. "The progressive supranuclear palsy-like brainstem predominant pattern of τ pathology and α-synuclein containing Lewy bodies in our SPG7 cases may be either coincidental or related to SPG7 in addition to neuron loss and neuritic pathology." (PMID 26506339, 2015).
mitochondrial disease (9 papers, 2014 to 2025). "Intriguingly, SPG7 appears to be the most common nuclear genetic cause of mitochondrial disease in adults to date." (PMID 26612854, 2015). "Three of these patients were subsequently found, on genetic testing, to have SPG7 and were therefore excluded from the mitochondrial group, leaving 27 patients in total with histologically suspected mitochondrial disease." (PMID 26640698, 2015). "In addition to well‐characterized cohorts, SPG7 alterations were frequently identified in cohorts with multisystemic mitochondrial disease and lower motoneuron lesions." (PMID 39978794, 2025). "Notably, mutations in SPG7 (≈4/100,000) and PEO1 (≈3/100,000), followed by OPA1 (≈1/100,000) and RRM2B (≈0.9/100,000) have emerged as major causes of adult mitochondrial disease." (PMID 25652200, 2015).
cancer (7 papers, 2016 to 2025). A tumor composed of atypical neoplastic, often pleomorphic cells that invade other tissues. "Lastly, MethylMix-PA also identifies hypo-methylation in the mitochondrial genes SPG7, speculatively linked to cancer through metabolic function." (PMID 31356589, 2019). "ECM proteases generally showed a widespread negative correlation with PEBP1/STK11 co-expression across all cancer types, with the exception of MMP15 and SPG7, which displayed positive correlations in most of the cancers analyzed." (PMID 40806276, 2025).
neurodegenerative disease (5 papers, 2010 to 2023). A disorder of the central nervous system characterized by gradual and progressive loss of neural tissue and neurologic function. "The SPG7 gene is implicated in the development of a genetically heterogeneous group of neurodegenerative diseases." (PMID 38138918, 2023). "This is in line with the fact that mutations in AFG3L2 or SPG7 lead to distinct neurodegenerative diseases, characterized by a pure neuronal and axonal phenotype, respectively." (PMID 27911893, 2016). "Over the past years, it has also been described in degenerative diseases, such as SCA48 and SPG7." (PMID 32340215, 2020).
neurological disease (4 papers, 2011 to 2019). "The m‐AAA protease plays crucial roles to maintain mitochondrial homeostasis in neurons, as underlined by the spectrum of neurological diseases associated with mutations in genes encoding the individual subunits SPG7 and AFG3L2." (PMID 30989755, 2019). "Our work provides a foundation to apply the powerful genetic tools of Drosophila to study the mechanisms underlying the neurological diseases associated with SPG7 mutations in humans." (PMID 29467464, 2018). "Mutations in SPG7, on the other hand, are associated with another type of m-AAA-associated neurological disease, autosomal recessive hereditary spastic paraplegia type 7 (SPG7; MIM #607259)." (PMID 22022284, 2011). "In addition, SPG7, which was highly methylated in ventrolateral prefrontal cortex, is an alternatively methylated gene involved in neurological disease." (PMID 31428131, 2019).
peripheral neuropathy (3 papers, 2023 to 2025). A disorder affecting the peripheral nervous system. "We also identified 7 patients with HPO terms representing a peripheral neuropathy and heterozygous pathogenic or likely pathogenic SPG7 mutations." (PMID 38549004, 2024).